APOE (apolipoprotein E)
Diseases named in the same sentence as APOE in open-access papers (continued):
Sharing a sentence is not in itself a finding about the gene and the disease.
Sepsis (34 papers, 2010 to 2026). Sepsis is defined as life-threatening organ dysfunction caused by a dysregulated host response to infection. "The analysis did not reveal statistically significant correlations, with a p‐value of 0.6592 for the association between APOE genotype and sepsis, and a p‐value of 0.4896 for the association between sepsis and SARS‐CoV‐2 in the lung." (PMID 41253293, 2025). "Among the plasma lipoproteins that are important host defense factors against S. typhimurium infection, apoE has been closely associated with sepsis." (PMID 37533741, 2023). "In another study, apolipoprotein E (APOE)-ɛ4 was found to be associated with the risk of sepsis development and progression." (PMID 36005151, 2022). "Our results support that APOE gene polymorphism contributed to the prognosis and development of sepsis." (PMID 32978453, 2020). "The present study used multicenter data to investigate the association between APOE gene polymorphism and sepsis." (PMID 32978453, 2020). "In the present study, we demonstrated that APOE polymorphism was associated with the progression of sepsis in a Chinese Han population." (PMID 32978453, 2020). "In this study, we investigated the association between sepsis and APOE in a multicenter case–control study." (PMID 32978453, 2020). "This study was to investigate the clinical relevance of the APOE gene polymorphism in the onset and progression of sepsis." (PMID 32978453, 2020). "ApoE is also known to regulate innate immunity and the susceptibility to bacterial infections and sepsis." (PMID 29789495, 2018). "Transgenic knock-in mice expressing the human APOE ε4 allele have increased morbidity and mortality in experimental sepsis models." (PMID 30412599, 2018). "It has been suggested that ApoE polymorphisms are associated with severe sepsis in surgical patients." (PMID 25242054, 2014). "In the current study, the impact of removal of the glucocorticoid function through adrenalectomy on the basal inflammatory status, sepsis susceptibility, and atherosclerotic lesion development was evaluated in hyperlipidemic APOE knockout mice." (PMID 24265824, 2013). "Previous studies had shown that ApoE genotype was associated with sepsis." (PMID 34825737, 2022). "As a disease closely related to inflammation, sepsis was studied in association with the polymorphism of APOE gene in the present study, and our results suggest that the APOEε4 allele contributed to aggravating the progression of sepsis from sepsis subtype to septic shock." (PMID 32978453, 2020). "Furthermore, the APOE ε4 allele has been associated with increased coagulation system failure in European Americans with severe sepsis." (PMID 30412599, 2018). "In addition, because apoE has been shown to protect against LPS-derived sepsis, apoE deficiency actually exposes mice to the deleterious and possibly proatherogenic effects of LPS." (PMID 24131481, 2013). "In striking contrast to the marked increase in sepsis susceptibility, the leukocytosis observed upon adrenalectomy however did not affect either the initiation or progression of atherosclerotic lesions in our APOE knockout mice." (PMID 24265824, 2013). "However, few genetic studies have associated the APOE gene polymorphism with sepsis." (PMID 32978453, 2020). "Furthermore, knocking out ApoE could confound interpretation of the link between inflammation and atheroma, as ApoE modulates the type I inflammatory response and ApoE polymorphisms are associated with sepsis susceptibility and outcomes." (PMID 25182529, 2014). "We demonstrated for the first time that an ApoE-based novel sHDL (YGZL3) effectively protected against septic death in two clinically relevant sepsis models." (PMID 40149933, 2025). "Using two mouse models of sepsis, we demonstrated for the first time that an ApoE-based novel type of sHDL nanoparticle provides effective protection against sepsis." (PMID 40149933, 2025).
Sepsis (continued). "Using two mouse models of sepsis, we demonstrate for the first time that an ApoE-based novel type of sHDL nanoparticle, YGZL3, provides effective protection against sepsis." (PMID 40149933, 2025). "We found that YGZL3, an ApoE sequence-based sHDL, provides effective protection against sepsis in two mouse models." (PMID 40149933, 2025). "We found that YGZL3, an ApoE-sequence-based sHDL, provided effective protection against sepsis in two mouse models." (PMID 40149933, 2025). "CETP inhibition improves Streptococcus pneumoniae–induced sepsis mortality in APOE*3-Leiden.CETP mice." (PMID 38646937, 2024). "Here, we show that treatment with the CETP inhibitor (CETPi) anacetrapib reduced mortality from Streptococcus pneumoniae–induced sepsis in APOE*3-Leiden.CETP and APOA1.CETP mice." (PMID 38646937, 2024). "Lipoproteins, including apoE, are known to play a key role in downregulating systemic inflammation in preclinical sepsis models and facilitating the clearance of gram-negative bacteria by binding to and neutralizing LPS." (PMID 37533741, 2023). "Studies using experimental animals that lack apoE have exhibited increased inflammatory responses in a sepsis model." (PMID 37111572, 2023). "The levels of VCAM1 (p = 0.010), B2M (p = 0.004), and ApoE (p = 0.039) were showing an increased tread in three groups, and B2M and ApoE were showing peak values in the sepsis group." (PMID 34825737, 2022). "The levels of VCAM1 (p = 0.010), B2M (p = 0.004), and ApoE (p = 0.039) were showing an increased tread in three groups, with the peak values of B2M and ApoE in the sepsis group." (PMID 34825737, 2022). "In this study, we developed a simple nomogram model (based on MAP, PLT, Cystatin C, HDL, and apoE) to predict MAKE30 in sepsis patients with T2DM." (PMID 36589822, 2022). "Increasing evidence has demonstrated that apoE is important in the pathophysiological course of anti-infection and anti-inflammation like sepsis." (PMID 36589822, 2022). "New diagnostic biomarkers of sepsis were screened by iTRAQ2D‐LC MS/MS, and proteins of ApoC3, VCAM1, B2M, and ApoE provide a supplement to classical biomarkers for septic diagnosis." (PMID 34825737, 2022). "In this study, the combination of ApoC3, VCAM1, B2M, and ApoE proteins were screened and identified as biomarkers for sepsis by using iTRAQ‐2D‐LC‐MS/MS method." (PMID 34825737, 2022). "APOE ɛ4 has also been shown to be related to the development of sepsis and enhances the attachment of Chlamydia pneumonia elementary bodies to host cells." (PMID 36005151, 2022). "To assess the transcriptional and translational changes in APOE under the sepsis condition, we also measured APOE mRNA expression and protein production of PBMCS extracted from another 21 healthy controls under LPS stimulation." (PMID 32978453, 2020). "We further divided the septic patients into two subgroups—of sepsis subtype and septic shock—based on the severity of sepsis, to assess the effect of APOE SNPs on the progression of sepsis." (PMID 32978453, 2020). "Genotypic distributions of APOE were consistent with Hardy–Weinberg equilibrium in the all sepsis patient and control groups." (PMID 32978453, 2020). "Next we measured the mRNA and protein levels of APOE with different genotypes under the sepsis condition." (PMID 32978453, 2020). "In this study, we confirmed that APOE mRNA levels were decreased in the blood during sepsis, which is consistent with the results of our in vitro experiments using LPS-stimulated PBMCs and RAW264.7 cells." (PMID 32978453, 2020). "Levels of Apolipoprotein E (Apo E) are often elevated in adult and pediatric patients during bacterial infection and sepsis." (PMID 30774579, 2019). "In contrast to most other acute phase proteins that involve de novo hepatic synthesis, these workers found that the increase in apoE during sepsis resulted from a combination of inhibition of apoE degradation and down-regulation of hepatic LDL receptors." (PMID 29807532, 2018).
Sepsis (continued). "The increase of ApoE in plasma has been reported during infections and sepsis, in animal models and patients, related with a LPS-clearance effect." (PMID 29030613, 2017). "Despite an increase in plasma levels of apoE in the LD50 sepsis‐group after 24 hrs, the transcription of apoE was strongly decreased in the liver at 12–34 hrs, which was the latest time‐point where tissue samples were available." (PMID 26990127, 2016). "Here, we will review the role of NKT cells in sepsis and septic shock, the immunoregulatory role of apoE in the host immune response to infection, and propose a mechanism for this immunoregulation." (PMID 20953368, 2010). "To explore potential associations, we applied Fisher's exact test to examine whether sepsis correlated with viral presence in the lung tissue as well as with different APOE genotypes (E3/E3, E3/E4, E4/E4)." (PMID 41253293, 2025). "The investigators hypothesized that VCAM1 reflected endothelium dysfunction, β2-microglobulin reflected sepsis-induced kidney, ApOC3 reflected hepatic secretory function, and ApoE reflected coagulation system failure." (PMID 36831207, 2023). "Corroborating with this findings, apoE protein levels are lower in patients with sepsis." (PMID 37111572, 2023). "An index combining the levels of four proteins (β2-microglobulin >3.7 mg/L, VCAM1 >2216.8 ng/mL, ApoC3 ≤54.532 μg/mL, ApoE >62.45 mg/L) and two conventional infection biomarkers (procalcitonin, C-reactive protein yielded an AUC of 0.772 for sepsis identification." (PMID 36831207, 2023). "In addition, this study showed that the serum level of ApoE was increased in sepsis and septic shock group, with a peak value in the sepsis group." (PMID 34825737, 2022). "Meanwhile the mechanism on effect of APOE protein in sepsis is still unclear." (PMID 32978453, 2020). "ApoE inhibited the lipopolysaccharide (LPS)-induced increase of tumor necrosis factor-α, interleukin (IL)-1β and IL-6 in serum and decreased the mortality rates of mice with sepsis." (PMID 25242054, 2014). "By contrast, another study suggested that ApoE increased the mortality rates of rats with sepsis." (PMID 25242054, 2014). "Therefore, it is suggested that ApoE demonstrated protective effects in the early stages of sepsis, but that this effect was reversed in the later stages." (PMID 25242054, 2014). "Although the role of ApoE in sepsis was not clear, ApoE was determined to be associated with a variety of different factors." (PMID 25242054, 2014). "In addition, APOE mRNA and the plasma protein levels decreased under the sepsis condition." (PMID 32978453, 2020). "These lines of evidence suggest that APOE may have anti-infective and anti-inflammatory properties, which play a significant role in the pathogenesis of directly inflammatory-related diseases, such as sepsis." (PMID 32978453, 2020). "Our future studies will focus on the mechanisms of APOE4 in the pathogenesis of sepsis and whether the APOEε4 allele can be used as an early warning signals of genetics or the APOE protein could be as a therapy target for the treatment of sepsis in clinical practice." (PMID 32978453, 2020). "However, the clinical relationship between APOE polymorphism and the development of sepsis is not well known, and clinical observations have been unsystematic." (PMID 32978453, 2020). "In this study we observed that the APOE protein seems to be consumed in the development of sepsis, the decreased mRNA level of APOE may lead to the decrease of protein level in pathological process of sepsis." (PMID 32978453, 2020). "Similarly to the LD100 sepsis group, apoE was decreased in the non‐survivors at 12–24 hrs." (PMID 26990127, 2016). "Consistent with the pro-inflammatory contribution that apoE may be making in sepsis, hypomorphic apoE mice (Apoeh/h) expressing 2–5% of wild-type serum levels of apoE were found to be less susceptible to septic mortality than their induced (wt apoE levels) counterparts [unpublished data]." (PMID 20953368, 2010).
Sepsis (continued). "We demonstrated that an ApoE-based sHDL nanoparticle, YGZL3, provides effective protection against CLP- and P. aeruginosa-induced sepsis." (PMID 40149933, 2025). "In sepsis patients with T2DM, Mean Arterial Pressure (MAP), Platelet (PLT), cystatin C, High-Density Lipoprotein (HDL), and apolipoprotein E (apoE) were independent predictors for MAKE30." (PMID 36589822, 2022). "In conclusion, our study demonstrated that in sepsis patients with T2DM, the levels of MAP, PLT, Cystatin C, HDL, and apoE available within 24 hours after admission played a critical role in MAKE30 prediction." (PMID 36589822, 2022). "Then, it revealed that in sepsis patients with T2DM, MAP (0.928,0.906-0.950), PLT (0.995,0.992-0.999), HDL (0.009,0.002-0.036), apoE (0.988,0.979-0.997), and cystatin C (1.960,0.360-2.826) were independent predictors for MAKE30." (PMID 36589822, 2022). "The application of the nomogram model is demonstrated by the following example: assuming a sepsis patient with T2DM with a MAP of 70 mmHg, a Cystatin C of 3 mg/L, an HDL of 1 mmol/L, a PLT of 200 x 109/L, and an apoE of 40 mg/L." (PMID 36589822, 2022). "We constructed a simple nomogram model to predict MAKE30 in sepsis patients with T2DM based on those independent predictors (MAP, PLT, Cystatin C, HDL, and apoE) within 24 hours of admission." (PMID 36589822, 2022). "The expression of ApoE, Anxa1, NGAL, S100a8 and S100a9 were all elevated in the progression of sepsis." (PMID 25242054, 2014). "In conclusion, the present study demonstrated that the expression of five proteins (ApoE, Anxa1, NGAL, protein S100a8 and S100a9) was significantly elevated in the progression of sepsis." (PMID 25242054, 2014). "In sepsis models induced by CLP, ApoE reversed the increase of hepatic T cell apoptosis and necrosis, and promoted Th1 cytokine levels." (PMID 25242054, 2014). "This evidence potentially expands apoE's role in promoting septic mortality to include mediating the presentation of not only PAMPs, but DAMPs as well, in a CLP model of sepsis." (PMID 20953368, 2010). "Similarly, lipid-regulating enzymes ANXA1, S100A8, and FABP5 are co-regulated in a network with ApoE and APP in response to sepsis." (PMID 38653992, 2024). "In addition, the survival in control-treated APOA1.CETP mice and APOE*3-Leiden.CETP mice was similar, despite differences in HDL-C levels, suggesting other factors beyond the HDL-C level that contributes to sepsis survival." (PMID 38646937, 2024). "In serum, increases in acute phase proteins were detected in both conditions and some proteins, such as APOE, showed significant changes in sepsis but not in non-septic inflammation." (PMID 35743177, 2022). "The APOE mRNA and protein levels in septic patients were significantly lower than those of the healthy controls (p = 0.024 and p < 0.001, respectively), while the levels of TNF-α, IL-6, and IL-1β were elevated in sepsis patients." (PMID 32978453, 2020). "Moreover, patients carrying APOE*3 have a lower incidence of developing severe sepsis in an elective surgical cohort compared with patients lacking APOE*3." (PMID 23957944, 2013).
brain injury (33 papers, 2013 to 2026). Acute and chronic (see also brain INJURIES, CHRONIC) injuries to the brain, including the cerebral hemispheres, CEREBELLUM, and brain STEM. "Despite the pathophysiological roles that APOE ε4 plays in TBI, studies associating APOE ε4 and sport-related concussion are few and findings are conflicting." (PMID 33499151, 2021). "Family history of AD, existence of one or more apolipoprotein E (ApoE) gene alleles, cardiovascular risk factors, and moderate or severe brain traumas can also account for the aetiology of the disease." (PMID 32545276, 2020). "Subcommittees of the American Academy of Neurology have suggested that the e4 allele of the ApoE gene is a risk factor for chronic neurobehavioral impairment following a concussion and should be examined further." (PMID 29910309, 2018). "Here, repeated mild brain trauma leads to trauma-induced tau hyperphosphorylation followed by activation of a various potential second-risk determinants like involvement of apolipoprotein E (ApoE) e4 allele and loss of TDP-43 nuclear function." (PMID 33921385, 2021). "The genes of particular interest for their potential effect on event-related potentials are Apolipoprotein E, Catechol-O-methyltransferase, and Dopamine Receptor D2, as they have been previously suggested to influence concussion susceptibility and cognitive function." (PMID 29910309, 2018). "Neurotransmission-related genes (BDNF, COMT, DRD1–3, DBH, SLC6A4, HTR2A, APOE) influenced motivation, fatigue, cognitive performance, and brain injury recovery." (PMID 41596414, 2026). "Hexosylceramide has been found to be associated with mild traumatic brain injury and PTSD, and the effects are influenced by APOE e4 status." (PMID 35484105, 2022). "For instance, Ngf, Pdgf-aa, Adap12, ApoE and Adcyap1 have been shown to promote neurogenesis and axonal outgrowth via multifaceted mechanisms following traumatic brain injury 44-47." (PMID 34987639, 2022). "Previous studies have shown that microglial exosomal miR-124 can downregulate USP14 to reduce neurodegeneration and promote synaptic growth in mice after traumatic brain injury through targeting Rela/ApoE signaling pathway." (PMID 36311808, 2022). "A recent study that used ApoE-KO mice demonstrated that increased ApoE expression mediated by bexarotene is necessary for reversion of traumatic brain injury-induced memory and learning impairment." (PMID 31596896, 2019). "The authors did not detect differences in concussion susceptibility attributable to APOE; however, the baseline reaction times of ε4 carriers were slower compared to other allele groups." (PMID 30223506, 2018). "Our null finding may be a consequence of low power but could also indicate our chosen recovery/severity metrics are not sensitive to identify APOE-associated differences in concussion severity and/or recovery." (PMID 39821585, 2025). "One study found limited evidence for altered fractional anisotropy (FA) in the cingulum of APOE ɛ4 carriers with concussion/mild traumatic brain injury, while another observed that military veterans who are APOE ɛ4 carriers may be more vulnerable to WM abnormalities after blast exposure." (PMID 39821585, 2025). "Various predisposing interacting factors may contribute to the road map for brain resilience, including education, gender, prior brain injuries, family history, participation in cognitively stimulating activities, physical exercise, social relationships and apoE genotype." (PMID 31465498, 2019). "After traumatic brain injury (TBI), ApoE regulated the microglial activation and inflammatory response by responding to a variety of acute or chronic injuries in the brain." (PMID 36081797, 2022). "Genetic polymorphisms in the genes contributing to plasticity and repair (APOE), synaptic connectivity (GRIN2A), calcium influx (CACNA1E), uptake and deposit of glutamate (SLC17A7) are potential biomarkers of concussion incidence and recovery rate." (PMID 30202567, 2017).